BCL2 (BCL2 apoptosis regulator)
Diseases named in the same sentence as BCL2 in open-access papers (continued):
Sharing a sentence is not in itself a finding about the gene and the disease.
cancer (continued). "Increased expression of Bcl-2 occurs in a variety of human cancer cells and tissues, where it can suppress a number of apoptotic death programs." (PMID 31108969, 2019). "BH-3 mimetics imitate protein–protein interactions between BH-3 domains and Bcl-2 family members, and have been used to displace bound Bcl-2 protein from pro-apoptotic partners, leading to cancer cell death." (PMID 31261935, 2019). "Responsible for the downregulation of caspase-3, which is an effector of mammalian cell death, Bcl-2 becomes overexpressed on the mitochondrial surface of cancer cells and is responsible for their anti-apoptotic properties." (PMID 31010150, 2019). "Increased expression of Bcl-2 has been observed in a variety of human cancer cells and tissues, where it can suppress a number of apoptotic death programs." (PMID 31178739, 2019). "Inhibiting the activities of anti-apoptotic BCL-2 members by drugs or neutralizing by BH3 peptides to prime cancer cells to death has been regarded as effective therapeutic modalities." (PMID 31683603, 2019). "Many apoptotic stimuli induce mitochondria-mediated apoptosis in cancer cells by downregulation of Bcl-2/Bax ratio, which is anti-apoptotic and/or up-regulation of Bax/Bad/Bid, which are pro-apoptotic." (PMID 30696035, 2019). "The family of anti-apoptotic B-cell lymphoma 2 (Bcl-2) proteins present an interesting target for cancer therapies because of their role in promoting cell survival inhibition of apoptosis." (PMID 31261935, 2019). "The Bax/Bcl-2 ratio can also be used to evaluate cell apoptosis, while its elevation induces apoptosis of cancer cells." (PMID 31509964, 2019). "Adding to the difficulty in navigating the BCL-2 targeting landscape, cancers derived from the same cell type can show different BCL-2 anti-apoptotic dependencies." (PMID 31692812, 2019). "The immunocytochemical analysis of Bcl-2 indicated that its expression was restricted to the invaded stroma and downregulated in moderately differentiated carcinoma." (PMID 30886526, 2019). "The identification of novel targets for cancer treatment is an area of intense work that has led Bcl-2 over-expression to be proposed as one of the hallmarks of cancer and Bcl-2 inhibition as a promising strategy for cancer treatment." (PMID 30544835, 2018). "Several BH3-mimetic small-molecule inhibitors that can selectively target BCL2 were recently evaluated in patients with cancer, including venetoclax (ABT-199) and S55746 (7, –9)." (PMID 30404918, 2018). "The ability to target and induce death of cancer cells with high levels of Bcl-2 represents a unique opportunity to treat chemoresistant cancers." (PMID 29899843, 2018). "The cancer cells usually prohibit the apoptotic program through increased expression of anti-apoptotic proteins such as Bcl-2 or BclXL or by decrease in expression of pro-apoptotic proteins such as Bax and Bak." (PMID 29755565, 2018). "In human cancers, the anti-apoptotic BCL-2 proteins play a critical role in protecting cells, which are often “primed” for apoptosis, from committing to irreversible cell death." (PMID 30158527, 2018). "In PEPE2-incubated T24 and J82 cells, the apoptosis-activator Bax level was increased while the anti-apoptotic Bcl-2 amount was decreased and thus, the pro-caspase-9 level dwindled, implying that the mitochondrial pathway was related to cancer cell apoptosis." (PMID 29702555, 2018). "The present study shows that besides physically inhibiting drugs from accessing cancer cells, the decellularised ECMs can upregulate anti-apoptotic genes such as Bcl-2 and Bcl-xL." (PMID 30241395, 2018). "Previously, several studies have reported its biological anti-cancer effects in hematological malignancies through cytotoxic effects, suppression of Bcl-2, and activation of Bax and caspase-3." (PMID 29671785, 2018). "Different BCL2 protein ratios have been previously used as a parameter to measure the sensitivity of a cancer cell population to undergo apoptosis." (PMID 29352235, 2018).
cancer (continued). "The balance of pro- and antiapoptotic BCL-2 proteins is crucial for cell survival and commonly exploited by cancer cells, which due to their exaggerated metabolism, oncogenic stress and cancer therapy are more primed for cell death." (PMID 30123424, 2018). "Navitoclax, in use to treat various types of cancer, targets BCL-2 proteins and thereby specifically kills cancer and senescent cells." (PMID 29547561, 2018). "Since selective BCL-2 inhibition is a promising treatment strategy in hematologic malignancies, we tested the therapeutic impact of ABT-199 on MDS patient samples bearing an adverse mutational profile." (PMID 29707107, 2018). "The active form of Bcl-2 was decreased, but the inactive form of Bcl-2 was increased in both HBITC-treated cancer cell lines (*p < 0.05)." (PMID 29508061, 2018). "Down-stream effects of SHetA2 binding to these proteins lead to degradation of cyclin D1 in both normal and cancer cells and Bcl-2 and Bcl-xl in cancer cells only." (PMID 29634717, 2018). "For example, BCL-2 has elevated gene expression in over half of all cancers and XIAP is overexpressed in many different tumors." (PMID 29393886, 2018). "Silencing the prosurvival pathways by Bcl-2 inhibitors would make cancer cells under integrated stress more sensitive to death." (PMID 29789637, 2018). "In VOE250 group with lower LDH level, the Ki-67 positive cancer cells were notably reduced and Bax/Bcl-2 ratio was enhanced." (PMID 29755559, 2018). "In light of our studies and reports from clinical trials with oncolytic adenoviruses, we expect that future clinical applications of viral mutants will be efficacious in combination with current clinical cytotoxic drugs in Bcl-2-positive cancers." (PMID 29362360, 2018). "Herein, we observed that gAcrp inhibited Bcl‐2 expression in HepG2 cells, which is accompanied with induction of caspase‐3 activity, suggesting that gAcrp induces apoptotic cell death triggered by suppression of Bcl‐2 in cancer cells." (PMID 30524947, 2018). "Another study showed that bufalin, a cardiotonic steroid, reduced the expressions of antiapoptotic protein Bcl-2 and surviving and increased the proapoptotic protein Bax/Bcl-2 rate in several different cancer types." (PMID 30046347, 2018). "It is reported that NF-κB can also influence the expression of BCL-2 proteins and that constitutive NF-κB activation has been observed in many cancers resistant to antitumor agents (including SK-OV-3 ovarian cancer cells)." (PMID 30267152, 2018). "Together, these results indicate that targeting overexpression of Bcl-2 with Bcl-2 functional converting peptides is a viable strategy to eliminate resistant cancer cells." (PMID 29899843, 2018). "The role in cancer development and the frequency of expression make Bcl-2 as a potential target for cancer gene therapy." (PMID 29861465, 2018). "Drugs targeting Mcl-1, and other Bcl-2 pro-survival proteins, are being developed as cancer therapies, and some of these inhibitors have advanced to clinical trials." (PMID 29928066, 2018). "Other proteins linking mitophagy with the development of cancer are Parkin, BCL2/adenovirus E1B 19-kDa interacting protein 3 (BNIP3) and AMBRA1." (PMID 30344951, 2018). "We chose these cancer cell lines because they have been consistently studied in the BCL-2 field and were used in our initial characterization of PTBP1’s impact on MCL18." (PMID 29748555, 2018). "The recognition of the important role played by BCL-2 for cancer development and resistance to treatment made it a relevant target for therapy for many diseases, including solid tumors and hematological neoplasias." (PMID 29747654, 2018).
cancer (continued). "Novel strategies, based on ectopic expression and genetic/pharmacological repression of specific BCL-2 proteins, “mito-prime” cancer cells against drug treatments." (PMID 29682179, 2018). "Cancer cells can acquire resistance to apoptosis (type I programmed cell death) by expressing anti-apoptotic proteins such as B-cell lymphoma 2 (BCL-2) or by downregulating pro-apoptotic proteins." (PMID 30344951, 2018). "LcS-geniposide also had the effects of increasing Bax and decreasing Bcl-2, Bcl-xL expression for killing cancer cells, these effects were similar to previous studies." (PMID 29751513, 2018). "The overexpression of pro-apoptotic proteins of the family Bcl-2 gives cancer cells a survival advantage in response to a wide range of apoptotic stimuli by inhibiting the release of mitochondrial cyt c." (PMID 30486451, 2018). "For instance, Bcl-2/Bcl-xL- inhibition coupled with the inhibitor WP1130 showed synergistic anti-cancer effects in several preclinical model systems." (PMID 30478285, 2018). "Dactolisib enhanced the downregulation of Bcl-2, which indicates that it improves treatment efficacy in part by promoting cancer cell apoptosis." (PMID 29416647, 2018). "MiR‐365 plays roles in the initiation and development of cancers by repressing bcl‐2 and cyclin D1/cdc25A expression." (PMID 29451327, 2018). "The BCL-2 proteins, consisting of both pro-apoptotic and antiapoptotic members, play a central role in cancer progression and in responses to both genotoxic and targeted therapies." (PMID 29374142, 2018). "Interactions between MSC and cancer cells in the bone marrow have been shown to promote survival of acute myelogenous leukemia through upregulation of anti-apoptotic bcl-2 with reduced rates of apoptosis in response to cytotoxic chemotherapy." (PMID 30526687, 2018). "Lipopeptides have been found to kill many types of cancer cells by inhibiting ERK1/2 and Akt activation, causing ROS burst, cell-cycle arrest, enhancing the bax-to-bcl-2 expression ratio, and caspase activation." (PMID 29777449, 2018). "While the small molecule inhibitor targeting BCL-2/BCL-xL/BCL-w (ABT-263) as a single agent has entered clinical experimentation in certain cancers, NSCLC is largely resistant to these inhibitors alone." (PMID 30250075, 2018). "Based on previous reports, it is well established that Bcl‐2 plays an important role in determination of apoptosis in cancer cells and its expression can be modulated by mRNA‐destabilizing proteins." (PMID 30524947, 2018). "SAL also inhibits K-ras, Notch and Hedgehog signaling, (ii) NIG is also a potent modulator of the Wnt signaling pathway and (iii) OBT targets cancer stem cells via disruption of BCL-2-dependent oxidative phosphorylation." (PMID 30262730, 2018). "In order to induce apoptosis in cancer cells, most therapies are based on stimulating the expression of Bax and/or suppressing Bcl-2 protein." (PMID 30419892, 2018). "Several reports have shown that Bcl-2 and Bcl-xL are involved in the development of resistance to paclitaxel in cancer cells." (PMID 29673198, 2018). "Another ER stress-mediated apoptosis protein is the C/EBP homologous protein (CHOP), which is also known as growth arrest- and DNA damage-inducible gene 153 (GADD153), which downregulates Bcl-2 and perturbs cancer cell oxidation/reduction or the redox state." (PMID 30598998, 2018). "Mechanistically, we demonstrate that hyperosmotic stress imposed a BCL-2-addiction on cancer cells to safeguard the integrity of the outer mitochondrial membrane (OMM), essentially exhausting the protective capacity of BCL-2-like pro-survival proteins." (PMID 29706657, 2018).
cancer (continued). "The delivery of siBcl-2 by LHRH-QPAMAM reduces Bcl-2 expression in cancer cells by more than by 75% and promotes accumulation in tumor and liver tissues in vivo." (PMID 30096839, 2018). "The results of this study and other data clearly indicate that Epo increases BCL-2 expression in numerous cancer cells." (PMID 29690619, 2018). "As such, BIRD-2 and ABT-199 can act synergistically to trigger cell death in Bcl-2-dependent cancers." (PMID 29491433, 2018). "Among the SNV top-ranked promoters (DMD), DHS elements (LRMP) and enhancers (PAX5, BACH2, BCL2, CXCR4, and BCL7A) are highly cancer-type-specific cases with many BCL or CLL mutations." (PMID 29354286, 2018). "Drugs, which can induce c-Bax generation, such as inhibition of AURKA by MLN8237, probably have a better response in Bcl-2 driven cancers." (PMID 30013101, 2018). "BCL2 selective inhibitors are promising agents currently under clinical investigation for treatment of BCL2-dependent cancers." (PMID 30404918, 2018). "Gene copy number increases in pro-survival BCL-2 members in cancer are more widespread than translocation." (PMID 29769323, 2018). "This highlights the potential of the Bcl-2 functional conversion strategy to treat and prevent therapy resistant cancers." (PMID 29899843, 2018). "Nevertheless, it seems that there is an interplay between ABT-199-induced cell death in Bcl-2-dependent cancer cells and basal Ca2+ signaling, since chelating intracellular Ca2+ using BAPTA-AM enhanced ABT-199-induced cell death." (PMID 29491433, 2018). "In this regard, BH3 mimetics have been developed to inhibit the activity of Bcl-2 and Bcl-xL in order to promote apoptosis to kill unwanted cancer cells." (PMID 30373097, 2018). "Unsurprisingly, the co-culture of this cancer cell line accompanied by hypoxia had the greatest increase in the BCL2 gene expression." (PMID 29849981, 2018). "B-cell lymphoma 2 (Bcl-2) family members such as Bcl-xL, are key regulators of apoptosis and as such Bcl-2 inhibitors have been developed to treat cancer." (PMID 30250466, 2018). "On the other hand, treatment of MDA-MB-231 cancer cells with conjugates 4m and 7b significantly downregulated the expression levels of the antiapoptotic protein Bcl-2 by 66.6 and 55.1%, respectively, compared to the control." (PMID 29895744, 2018). "The Nur77 derived peptide preferentially induced apoptosis in paclitaxel-resistant cancer cells with high expression of Bcl-2." (PMID 29899843, 2018). "It has been demonstrated that gossypol binds to the BH3 binding groove of anti-apoptotic Bcl-2 proteins, thus inhibiting the anti-apoptotic function of Bcl-2, Bcl-xl, and Mcl-1, and inducing apoptosis of cancer cells." (PMID 30459622, 2018). "With these limitations in mind, we set out to address the following questions: What are the dependencies of diverse human cancers with respect to BCL-2, BCL-XL, MCL-1, and their combinations?" (PMID 30158527, 2018). "BH3-mimetic compounds, like venetoclax, disrupt the binding between Bcl-2 and pro-apoptotic BH3-only proteins, thereby triggering apoptotic cell death in cancer cells that depend on Bcl-2's function at the mitochondria for their survival." (PMID 30416758, 2018). "Based on the binding site of Bcl-2 on the IP3R, a peptide tool was developed in an attempt to target pro-survival Bcl-2 proteins at the ER in cancer cells." (PMID 30416758, 2018). "ANXA3 correlates also with cell proliferation as indicated by Ki-67 and Bcl-2 expression and appears to be preferentially expressed in cancer stem-like cells/cancer initiating cells (CSCs/CICs)." (PMID 29423100, 2018). "Overexpression of Bcl-2 can inhibit cell apoptosis, lead to resistance to cisplatin, and result in poor prognosis of cancer patients." (PMID 30454003, 2018).
cancer (continued). "As a result, over the last years, there was an explosive output of research focused on the role of BCL-2 and its family members in apoptosis’ regulation, cancer development, and resistance to treatment." (PMID 29747654, 2018). "Bcl-2 was also phosphorylated at the serine 70 residue within the loop domain in the paclitaxel resistant cancer cells, which enhances Bcl-2 anti-apoptotic activity." (PMID 29899843, 2018). "The BIRD-2 peptide provokes IP3-induced Ca2+ release in cancer cells that depend for their survival on the function of Bcl-2 at the ER." (PMID 30416758, 2018). "Deregulation of BCL-2 proteins is now recognized as a frequent event in many types of cancer and it seems likely that targeting pro-survival BCL-2 proteins will form a valuable adjunct to current cancer therapies." (PMID 29769323, 2018). "Gene expression analysis revealed that Curcumin decreases the expression of anti-apoptotic protein; Bcl-2 and increases the expression of pro-apoptotic protein Bax in cancer cell lines." (PMID 29755534, 2018). "Mechanistically, hyperosmotic stress enforced BCL-2 addiction of cancer cells and thereby decreased the remaining capacity of mitochondria-safeguarding BCL-2-like proteins." (PMID 29706657, 2018). "According to previous study, LCA can inhibit BCL2 for inducing autophagy and promoting apoptosis in cancer cells." (PMID 30400936, 2018). "We have generated ARTS‐based small molecule mimetics which were found to reduce the endogenous levels of XIAP and Bcl‐2 in cancer cells and promote apoptosis." (PMID 29460395, 2018). "Silencing of procaspase-3 and Bcl-2 expression by (chondroitin sulfate)-PAMAM-miR-34a complexes led to an increase in the apoptotic fraction of cancer cells (22% vs. 6% in controls)." (PMID 30096839, 2018). "In many cancer cells, overexpression of prosurvival factors, such as Bcl-2, Bcl-xL, and Mcl-1, contributes to resistance to anticancer agents." (PMID 29642569, 2018). "Is there a difference between subcellular distribution of Bcl-2 proteins between normal and cancer cells and if so, does this difference contribute to cancer progression or chemoresistance represents another open question." (PMID 29497611, 2018). "BIRD-2 was shown to kill Bcl-2-dependent cancer cells, like DLBCL and CLL cells, by eliciting spontaneous, pro-apoptotic Ca2+ signals." (PMID 30416758, 2018). "The BCL-2 protein is the founding member of the BCL-2 family of apoptosis regulators and was the first apoptosis modulator to be associated with cancer." (PMID 29747654, 2018). "These are only a few examples of questions that remain and, clearly, much work remains to be done as we continue to explore ways to harness the activity of BCL-2-selective inhibitors for cancer therapy." (PMID 30406027, 2018). "Bax and Bcl-2 are mitochondrial proteins, while Bax exhibits pro-apoptotic activity, Bcl-2 is considered an anti-apoptotic and is often overexpressed in different cancers." (PMID 30419892, 2018). "(A) The oncogenic signal NF-kB was redirected to activate two tumor suppressors, Bax and p21, and to suppress two oncogenes, BCL2 and c-Myc, by the signal-connector in the cancer cells." (PMID 29319503, 2018). "Decreased expression of pro-apoptotic BCL-2 proteins has the same functional outcome as increased pro-survival expression in cancer." (PMID 29769323, 2018). "In a subset of these cancer cells, Bcl-2 blocks Ca2+-mediated apoptosis by suppressing the function of inositol 1,4,5-trisphosphate (IP3) receptors (IP3Rs) located at the endoplasmic reticulum (ER)." (PMID 30416758, 2018). "The vast majority of traditional anticancer drugs depend on BCL-2/BAX-dependent mechanisms to kill cancer cells." (PMID 29393886, 2018). "BH3-mimetics comprise a novel class of BCL-2 inhibitors that have shown promising results in several hematological malignancies, both as single agents and in combination with other anti-cancer drugs." (PMID 29747654, 2018).